IFITM3 (interferon induced transmembrane protein 3)
Diseases named in the same sentence as IFITM3 in open-access papers (continued):
Sharing a sentence is not in itself a finding about the gene and the disease.
lung adenocarcinoma (5 papers, 2014 to 2025). A carcinoma that arises from the lung and is characterized by the presence of malignant glandular epithelial cells. "IFITM3 (Interferon-Induced Transmembrane Protein 3) (average methylation 21%, p = 0.03) regulates the growth and invasion of human lung adenocarcinoma and is believed to be a crucial factor in promoting carcinogenesis." (PMID 38791918, 2024). "For this, we engineered the human lung adenocarcinoma cell line A549 to stably express IFITM3 and analyzed the effects of an IFITM3-specific siRNA on S protein-mediated transduction." (PMID 25256397, 2014). "This pattern was further confirmed in an independent dataset comprising 21 SCLC samples, 24 lung adenocarcinoma (LUAD) samples, and four normal lung tissues, which consistently showed reduced IFITM3 expression in SCLC." (PMID 40611157, 2025).
Stroke (5 papers, 2022 to 2024). Sudden impairment of blood flow to a part of the brain due to occlusion or rupture of an artery to the brain. "Data from a study by Harmon and colleagues showed that ischemic injury in aged brains following stroke resulted in the induction of IFITM3 proteins." (PMID 38218875, 2024). "Increased expression of IFITM3 has been reported in stroke and other inflammatory conditions in the brain, including AD." (PMID 37440496, 2023). "Other MG markers, such as Lgals3, Ifitm3 and Lgals3bp, were also upregulated in MG and other cells following stroke." (PMID 36824976, 2023). "Future studies are needed to evaluate the role of IFITM3 in modifying neuroinflammation via infiltrating peripheral immune cells in stroke, AD, and other neurodegenerative diseases." (PMID 36012150, 2022). "We showed increased IFITM3 expression in primary microglia and Sim-A9 cells exposed to pro-inflammatory mediators and found increased IFITM3 expression in peri-infarct regions of aged brains following stroke." (PMID 36012150, 2022). "We next examined the expression profile of IFITM family members (Ifitm1, Ifitm2, and Ifitm3) in the post-stroke brain of aged mice." (PMID 36012150, 2022). "In this study, we present data demonstrating that IFITM3 is a critically induced gene in various inflammatory situations, including in post-stroke brains in vivo and pro-inflammatory cytokine-stimulated primary microglia and microglial cell lines in vitro." (PMID 36012150, 2022). "Stitched images show increased expression of IFITM3 in the striatum and peri-infarcted cortex 7 days after stroke and this induction was reduced at 14 days after stroke." (PMID 36012150, 2022). "Since AD is another aging-related disorder with upregulation of IFITM3, we speculated that induction of IFITM3 may also play a role in stroke brains." (PMID 36012150, 2022). "This fundamental study will provide the solid foundation for future exploration of the role of IFITM3 in aging-related neurodegenerative diseases, including stroke, and to further identify IFITM3 as a critical mediator between neuroinflammation and neurodegeneration in the brain." (PMID 36012150, 2022). "Our findings on the expression of IFITM3 in microglia and in aged brains following stroke could establish the basic foundations for the role of IFITM3 in a variety of neurodegenerative diseases, particularly those that are prevalent or enhanced in the aged brain." (PMID 36012150, 2022). "The top five genes that were significantly upregulated in MG in the aged stroke brain included MG related genes (Lgals3, Lyz2, Lgals3bp) and another interferon-stimulated gene (ISG), Ifitm3." (PMID 36824976, 2023). "Brains were isolated at post-stroke day (PSD) 7 and 14 for immunostaining for IFITM3." (PMID 36012150, 2022). "The expression patterns and role of genes belonging to the IFITM family, especially IFITM3, in aged brains following stroke or with stressed primary microglia has not been revealed." (PMID 36012150, 2022). "However, there were not directed evidences showed that stroke and other inflammatory conditions did not induce astrocyte glial cells and neurons IFITM3 expression in different region of aged brain." (PMID 37602193, 2023). "Expression of IFITM3 in glial cells, especially microglia following stroke, is not well described." (PMID 36012150, 2022).
asthma (4 papers, 2022 to 2024). "Additionally, we observed a decrease in PGRN expression and an increase in IFITM3 and 14‐3‐3σ expression in the B cells of asthma patients." (PMID 39412083, 2024). "In total, 6 genes were upregulated (e.g. CCL3L1, CCL4L2, GPR82) and 20 were downregulated (e.g. JUN, IFITM3, DUSP1, GNG7) in peripheral eosinophils of COPD patients compared to asthma." (PMID 39422548, 2024). "Moreover, we established a house dust mite (HDM)‐induced asthma mouse model and found that PGRN expression was also reduced in the mouse model, while IFITM3 and 14‐3‐3σ expression increased consistent with asthma patients." (PMID 39412083, 2024).
colitis (4 papers, 2022 to 2025). Inflammation of the colon. "IFITM3 also significantly improves the incidence of colitis and prevents inflammation-associated tumorigenesis." (PMID 38543696, 2024). "Studies have demonstrated that the absence of the IFITM3 gene can lead to exacerbated inflammatory reactions and an increased incidence of tumor development in mice with chemically induced colitis." (PMID 40433377, 2025).
glioblastoma (4 papers, 2016 to 2025). The most malignant astrocytic tumor (WHO grade IV). "In glioblastoma, bFGF is upregulated by JAK/STAT3 activation, and induced by a glioblastoma stem cell-derived protein, Interferon-Induced Transmembrane Protein 3 (IFITM3), which subsequently promotes angiogenesis and metastasis." (PMID 39796710, 2024). "TCGA-based analysis of glioblastoma patient survival indicated a highly significant correlation between IFITM3 expression and diminished survival." (PMID 27835870, 2016). "Furthermore, a high expression of IFITM3 was correlated with a poor overall survival of GBM patients according to the Cancer Genome Atlas (TCGA) glioblastoma dataset." (PMID 27835870, 2016).
H1N1 influenza (4 papers, 2013 to 2022). "The severity of the 2009 H1N1 influenza pandemic is correlated with the rs34481144 allele, which modifies the binding affinity of the transcription factor of the IFITM3 gene." (PMID 36403064, 2022). "A statistically significant number of hospitalized subjects with H1N1 influenza had the IFITM3 rs12252 allele." (PMID 34434219, 2021). "Recently, one of the interferon-induced transmembrane (IFITM) family proteins, IFITM3, has become an important target for the activity against influenza A (H1N1) virus infection." (PMID 24058703, 2013). "In particular, IFITM3 has been a target of intensive studies on its activity against influenza A (H1N1) virus infection and internalization." (PMID 24058703, 2013). "In this study, we evaluated whether the bulk mRNA expression of IFITM1 and IFITM3 showed a particular pattern and dynamics during active severe pandemic influenza A(H1N1) virus infection in humans." (PMID 35708622, 2022).
lung carcinoma (4 papers, 2011 to 2024). "Knockdown of IFITM3 is effective in suppressing lung cancer cell proliferation, invasion, and migration while inducing cell cycle arrest and apoptosis." (PMID 38791918, 2024). "IFITM3 expression is positively correlated with cancer stage and differentiation status with higher expression levels in invasive ductal carcinomas as compared to ductal carcinoma in-situs and non-differentiated lung cancers as compared to well-differentiated lung cancers." (PMID 33364194, 2020).
neuroblastoma (4 papers, 2013 to 2025). Neuroblastoma (NB) is the most common solid, extracranial childhood tumor. "The IFITM family (in humans, five IFITM members: IFITM1, IFITM2, IFITM3, IFITM5, and IFITM10; in mice, seven Ifitm members: IFITM1, IFITM2, IFITM3, IFITM5, IFITM6, IFITM7, IFITM10) was first discovered as interferon-induced genes in human neuroblastoma cells." (PMID 36012150, 2022). "Interferon induced transmembrane protein 3 (IFITM3, also known as 1-8U) was initially identified in a cDNA screen from INF-treated neuroblastoma cell back in 1984 and cloned from a human lymphoid cell cDNA library." (PMID 24370119, 2013).
oral squamous cell carcinoma (4 papers, 2015 to 2024). "Interferon-inducible transmembrane (IFITM) was up-regulated in oral squamous cell carcinoma (OSCC), and IFITM3 knockdown inhibited OSCC cell proliferation by down-regulated the complex level of CCND1-CDK4." (PMID 38546402, 2024).
Sepsis (4 papers, 2022 to 2025). Sepsis is defined as life-threatening organ dysfunction caused by a dysregulated host response to infection. "Our results confirmed for the first time that IFITM3 is a pro-apoptotic protein involved in the occurrence of pathological brain damage caused by sepsis." (PMID 37602193, 2023). "Upregulation of platelet IFITM3 during clinical sepsis is associated with increased fibrinogen endocytosis and enhanced platelet reactivity." (PMID 36194487, 2022). "In contrast, IFITM3 protein was highly expressed and significantly upregulated in platelets isolated from the majority of sepsis patients." (PMID 36194487, 2022). "This suggests that during experimental sepsis, increased platelet Ifitm3 expression and aggregation is mediated by IFN-α." (PMID 36194487, 2022). "During sepsis and under inflammatory stress, IFITM3 alters lipid raft localization of critical platelet proteins such as clathrin and αIIb." (PMID 36194487, 2022). "Our findings that platelet IFITM3 mRNA remains elevated 90 days after discharge in recovered sepsis patients implicate IFITM3 as a potential regulator of postsepsis thrombosis." (PMID 36194487, 2022). "Consistent with the increase in Ifitm3 mRNA at day 3 after CLP, a significant increase in Ifitm3 protein was also observed in platelets following CLP sepsis." (PMID 36194487, 2022). "This study aims to explore whether interferon-induced transmembrane protein 3 (IFITM3) is involved in recombinant human brain natriuretic peptide (rhBNP)-mediated effects on sepsis-induced cognitive dysfunction in mice." (PMID 37602193, 2023). "Given the vital role of cGMP in the signaling pathway mediated by IFN and NPs, we speculate that rhBNP may have a certain effect on the expression of IFITM3 in the brain astrocytes of mice with sepsis." (PMID 37602193, 2023). "As the transcript for IFITM3 was upregulated in platelets during sepsis, we next determined whether IFITM3 protein expression in platelets was coordinately increased." (PMID 36194487, 2022). "Sepsis-induced platelet hyperreactivity in mice is regulated by IFITM3." (PMID 36194487, 2022). "As patients with sepsis are at increased risk for longer-term thrombotic complications even after their sepsis has resolved, we longitudinally examined platelet IFITM3 expression acutely in septic patients and again, 90 days later, in the same septic patients who had recovered." (PMID 36194487, 2022). "However, little is known about whether IFITM3 is involved in the occurrence and biological expression of sepsis-induced brain injury and cognitive impairment." (PMID 37602193, 2023). "Therefore, we have reason to believe that during the development of sepsis, astrocytes in the central nervous system are overactivated and release IFITM3, which acts on neuronal surface sites and disrupts the glial–neuron interaction, thereby damaging the brain." (PMID 37602193, 2023). "Interestingly, while lower than during acute sepsis, the expression of IFITM3 RNA remained significantly elevated in recovered septic patients compared with healthy donors, suggesting sepsis may trigger durable changes to the platelet transcriptome." (PMID 36194487, 2022). "Importantly, increased expression of IFITM3 on platelets from nonviral sepsis patients was associated with increases in fibrinogen endocytosis and platelet hyperactivity as well as shifting of clathrin and αIIb into platelet lipid rafts." (PMID 36194487, 2022). "Our clinical observations indicate that patients with nonviral sepsis have increased platelet IFITM3 expression." (PMID 36194487, 2022). "Here, we demonstrate IFITM3 is upregulated in platelets isolated from acutely infected patients with nonviral sepsis." (PMID 36194487, 2022). "Nonviral sepsis upregulated IFN-induced transmembrane protein 3 (IFITM3), an IFN-responsive gene that restricts viral replication." (PMID 36194487, 2022).
Sepsis (continued). "Taken together, these data indicate that in health, IFITM3 is transcriptionally and translationally silent in platelets and that during nonviral sepsis, IFITM3 mRNA and protein are actively made." (PMID 36194487, 2022). "Platelets from patients with nonviral sepsis had increases in platelet IFITM3 expression, fibrinogen content, and hyperreactivity." (PMID 36194487, 2022). "In conclusion, nonviral sepsis upregulates IFITM3 in platelets and megakaryocytes." (PMID 36194487, 2022). "Nonviral sepsis induces an increase in platelet IFITM3 expression." (PMID 36194487, 2022). "Given the increases in both IFITM3 mRNA and protein during nonviral sepsis, we speculated that IFITM3 may have noncanonical roles in hemostasis and thrombosis during nonviral sepsis, a concept not examined previously, to the best of our knowledge, in megakaryocytes or platelets." (PMID 36194487, 2022). "However, whether IFITM3 plays a role in sepsis-induced neuronal apoptosis has not been reported." (PMID 37602193, 2023). "Interestingly, IFN-α levels modestly and negatively correlated with IFITM3 expression in nonviral sepsis patients, suggesting that in our patient cohort, systemic IFN-α levels may have been high before enrollment and were decreasing at the time we collected blood samples." (PMID 36194487, 2022). "While the antiviral role of IFITM3 is well established, whether IFITM3 orchestrates CME in megakaryocytes and platelets and whether this results in prothrombotic responses in nonviral sepsis has not previously been examined." (PMID 36194487, 2022).
ulcerative colitis (4 papers, 2013 to 2024). An inflammatory bowel disease involving the mucosal surface of the large intestine and rectum. "Genetic polymorphisms in IFITM3 have been associated with susceptibility to ulcerative colitis." (PMID 39459876, 2024). "Researchers found that IFITM3 gene was mainly isolated from severely inflamed mucosa and considered as a biomarker for ulcerative colitis." (PMID 29088728, 2017). "Researchers first isolated the IFITM3 gene from tumor tissue and severely inflamed mucosa in the colons of patients with ulcerative colitis, describing it as a preferential marker for ulcerative colitis-associated colon cancer." (PMID 24370119, 2013). "Similarly, increased IFITM3 expression has been observed in the inflamed mucosa of patients with ulcerative colitis and Crohn’s disease." (PMID 39459876, 2024). "In addition, upregulation of IFITM3 was also found in precancerous tissues, such as in ulcerative colitis." (PMID 34456915, 2021). "Recent studies identified that IFITM3 gene was a powerful biomarker for ulcerative colitis." (PMID 29088728, 2017).
viral pneumonia (4 papers, 2015 to 2021). Inflammation of the lung parenchyma that is caused by a viral infection. "To our surprise, we found the anti-virus protein IFITM3 was expressed much lower than other tissues and organs, which could explain the mechanism of viral pneumonia resulting in profound morbidity." (PMID 33061814, 2020). "Knockout mice lacking normal IFITM3 were observed to develop fulminant viral pneumonia when exposed to a low-pathogenicity influenza virus." (PMID 34434219, 2021).
atherosclerosis (3 papers, 2022 to 2025). A disease characterized by the build-up of fatty material and calcium deposition in the arterial wall resulting in partial or complete occlusion of the arterial lumen. "IFITM1 and IFITM3 are two interferon-induced transmembrane proteins that might play significant roles in the pathophysiology of atherosclerosis, particularly through their involvement in inflammation, endothelial function, and vascular health." (PMID 40607379, 2025). "Although other genes in the module are not involved in the fluid shear stress and atherosclerosis pathway, S100a6 and Ifitm3 are known to regulate PI3K signaling, a sub-pathway of the fluid shear stress and atherosclerosis pathway." (PMID 36207684, 2022).
cervical cancer (3 papers, 2022 to 2025). A primary or metastatic malignant neoplasm involving the cervix. "In this regard, in our previous work, we identified a distinct subgroup of cervical cancer patients wherein IFITM1/IFITM3 proteins were highly expressed in cervical cancers." (PMID 36008984, 2022). "It was previously demonstrated that knocking out the IFITM1 and IFITM3 proteins led to the downregulation of HLA-B expression on the surface of cervical cancer cells, suggesting an explanation for the inverse correlation between IFITM1/3 expression and metastasis formation." (PMID 40314078, 2025). "Notably, IFITM3 has also been shown to modulate the tumor microenvironment by promoting CD8+ T-cell infiltration, which is essential for antitumor immunity, whereas its deficiency disrupts antigen processing and presentation in cervical cancer cells." (PMID 40611157, 2025). "Furthermore, the proteomic and gene expression data are supported by functional studies demonstrating the impact of the IFITM1 and IFITM3 proteins on the adhesive, migratory and invasive capabilities of cervical cancer cells, as well as their interactions with immune cells." (PMID 40314078, 2025).
co-infection (3 papers, 2021 to 2025). "Co-expression of IFI6, IFITM1 and IFITM3 across lymphoid tissues may be connected to enhanced pathogenesis in co-infection." (PMID 40211134, 2025). "In this context, the downregulation of IFITM3 by HSV1 coinfection could enhance HIV infectivity, as evidenced by the increase in HIV1 productive replication." (PMID 39476027, 2024).
diabetes (3 papers, 2017 to 2023). "In this study, we investigated the association between mild flu and IFITM3 rs12252 variant, BMI, diabetes, and hypercholesterolemia in an Iranian population." (PMID 29121968, 2017). "Compared to the findings in normal mice, FN-γ, SOCS1, STAT3, IFITM3, IRF3, and JAK2 expression was significantly higher in spleen cells from mice with diabetes, suggesting homeostatic inflammation was induced." (PMID 37110462, 2023). "SEA-treated spleen cells from mice with diabetes exhibited little change in the expression of STAT3, IFITM3, and JAK2." (PMID 37110462, 2023).
esophageal cancer (3 papers, 2015 to 2024). A primary or metastatic malignant neoplasm involving the esophagus. "Statistical analysis showed a significant correlation of IFITM3 expression with the T status of esophageal cancer (p = 0.015)." (PMID 26539332, 2015). "We found that among various IFITMs, only IFITM1 and IFITM3 were highly expressed in tumor tissues from both colon adenocarcinoma (COAD) and esophageal carcinoma (ESCA) patients as compared to normal tissue." (PMID 38167862, 2024).
head and neck squamous cell carcinoma (3 papers, 2020 to 2022). A squamous cell carcinoma that arises from any of the following anatomic sites: lip and oral cavity, nasal cavity, paranasal sinuses, pharynx, larynx, and salivary glands. "Overexpression of IFITM3 was correlated with poor prognosis and associated with some molecules of immune checkpoint and biomarkers of tumor-associated macrophage in head and neck squamous cell carcinoma." (PMID 33384961, 2020).